GPRC5A (G protein-coupled receptor class C group 5 member A)
Diseases named in the same sentence as GPRC5A in open-access papers (continued):
Sharing a sentence is not in itself a finding about the gene and the disease.
cyst (3 papers, 2022 to 2025). A sac-like closed membranous structure that may be empty or contain fluid or amorphous material. "In ADPKD, GPRC5A is overexpressed in cyst-lining epithelial cells, particularly during the early stages of cyst development." (PMID 40801635, 2025). "Through analysis of these multimodal datasets, we identified a G-protein-coupled receptor GPRC5A as a novel cyst marker in both human and mouse kidneys." (PMID 40281349, 2025). "Collectively, these findings suggest a potential role of ROR1 and GPRC5A in defining a unique gene signature of cyst-lining cells in ADPKD." (PMID 36310237, 2022). "Immunofluorescence studies validated GPRC5A expression in CDH1 + cyst-lining cells (left), while its expression was faint in CDH1 + tubular cells in control kidneys (right)." (PMID 36310237, 2022). "We identify GPRC5A as a marker for cyst-lining collecting duct cells that exhibits increased transcription factor binding motif availability for NF-κB, TEAD, CREB and retinoic acid receptors." (PMID 36310237, 2022). "We identified a GPRC5A + CDH1 + PC lineage (PKD-CDC1) in cyst-lining cells." (PMID 36310237, 2022). "Interestingly, we observed ROR1 protein expression in GPRC5A + cyst cells." (PMID 36310237, 2022). "Thus, GPRC5A might confer resistance to hypoxia in cyst cells, potentially promoting cyst growth in ADPKD." (PMID 36310237, 2022). "To characterize epigenetic mechanisms driving cyst growth, we predicted the cis-coaccessibility network in ADPKD kidneys around the MIR31HG or GPRC5A genes with Cicero9." (PMID 36310237, 2022). "It is tempting to speculate that upregulation of GPRC5A and ROR1 in cyst-lining cells might drive proliferation in the hypoxic milieu in ADPKD kidneys." (PMID 36310237, 2022). "Hence, GPRC5A may have a role in PKD progression through modifying the survival and proliferation of cyst cells." (PMID 40281349, 2025).
lung squamous cell carcinoma (3 papers, 2017 to 2021). "Meanwhile, although several mutation sites in GPRC5A gene were reported in human tumors, they were mainly discovered in other tumors, for instance uterine endometrioid carcinoma, lung squamous cell carcinoma and bladder urothelial carcinoma, none mutation has been tested for GPRC5A gene in PAAD." (PMID 34819098, 2021).
oral squamous cell carcinoma (3 papers, 2014 to 2023). "GPRC5A and oral squamous cell carcinoma: GPRC5A expression level is very high in normal oral tissue, especially in differentiated areas whereas in oral squamous cell carcinoma (OSCC) its expression is repressed." (PMID 25621293, 2014).
squamous cell carcinoma (3 papers, 2020 to 2023). A carcinoma arising from squamous epithelial cells. "An early study demonstrated that RAI3 expression, also named G protein-coupled receptor family C group 5 member A (GPRC5A) or RA-inducible gene 1 (RAIG1), is induced by ATRA exposure in squamous carcinoma cell lines." (PMID 32012980, 2020). "The results showed that GPRC5A expression was significantly repressed, whereas active p65 was greatly increased, in most of NSCLC, including squamous cell carcinoma (SCC) and adenocarcinoma (ADC), and all COPD tissues, compared with that in adjacent normal (AN) lung tissues." (PMID 36413416, 2023).
asthma (2 papers, 2021 to 2022). "This indicates that SERPINE1 and GPRC5A mRNA levels can identify the eosinophilic subtype of a severe asthma phenotype." (PMID 34088958, 2021). "Several genes such as SERPINE1, GPRC5A, SFN, ABCA1, MKI67, and RRM2 have been found to be downregulated in severe uncontrolled asthma using PBMCs and, therefore, potential biomarkers." (PMID 36294997, 2022). "SERPINE1 and GPRC5A were downregulated in the blood of eosinophilic asthmatics, while RRM2 was upregulated in an acute attack of asthma." (PMID 34088958, 2021). "Validation of the gene expression in PBMC of locally recruited asthma patients showed that SERPINE1, GPRC5A, SFN, ABCA1, MKI67, and RRM2 were downregulated in severe uncontrolled asthma." (PMID 34088958, 2021).
autoimmune disease (2 papers, 2015 to 2021). A disorder resulting from loss of function or tissue destruction of an organ or multiple organs, arising from humoral or cellular immune responses of the individual to their own tissue constituents. "Nevertheless, by generating miR-31 and its target Gprc5a DKO mice we clearly show that miR-31 promotes the development of autoimmune disease through inhibiting Gprc5a." (PMID 26165721, 2015). "Gprc5a deficiency resulted in a significant decrease in the percentage of pTreg cells compared with WT controls, suggesting that Gprc5a is critically required for pTreg-cell generation in vivo in autoimmune disease." (PMID 26165721, 2015). "Thus, our data identify miR-31 and its target Gprc5a as critical regulators for pTreg-cell generation, suggesting a previously unrecognized epigenetic mechanism for dysfunctional Treg cells in autoimmune diseases." (PMID 26165721, 2015). "However, the molecular mechanism by which Gprc5a promotes Treg-cell generation and suppresses autoimmune disease is subjected to further investigation." (PMID 26165721, 2015).
Autoimmunity (2 papers, 2015 to 2025). The occurrence of an immune reaction against the organism's own cells or tissues. "Conversely, by suppressing SH2 domain containing 1A (SH2D1A) and GPRC5A, miR‐31 promotes Th1 cytokine transcription but suppresses Treg generation, thus promoting autoimmunity in sepsis and experimental autoimmune encephalomyelitis." (PMID 40068094, 2025). "Thus, our findings demonstrated that miR-31 negatively regulated pTreg-cell generation by targeting Gprc5a, suggesting a novel epigenetic mechanism for impaired pTreg-cell induction in autoimmunity." (PMID 26165721, 2015). "The functional analysis of Gprc5a in T-cell differentiation and autoimmunity is not yet performed." (PMID 26165721, 2015).
diabetic nephropathy (2 papers, 2021 to 2022). "However, one study showed that lncRNA MIAT blocked the high glucose-mediated cell damage and activation of NF-κB via sponging miR-182-5p and elevating the GPRC5A expression in diabetic nephropathy, leading to suppression of diabetic nephropathy progression." (PMID 36313695, 2022).
injury (2 papers, 2015 to 2023). Damage inflicted on the body as the direct or indirect result of an external force, with or without disruption of structural continuity. "Previously, we showed that, Gprc5a−/− mice are susceptible to both lung tumorigenesis and endotoxin-induced acute lung injury." (PMID 26447616, 2015). "Moreover, Gprc5a−/− mice were sensitive to inflammation-promoted lung tumorigenesis and endotoxin-induced acute lung injury." (PMID 26447616, 2015).
leukoplakia (2 papers, 2017 to 2018). A white patch or plaque on a mucous membrane that cannot be characterized clinically or pathologically as any other disease. "In oral premalignant leukoplakias, the tumor suppressor GPRC5A (G protein-coupled receptor family C group 5 member A) is repressed, allowing for the inflammatory mediator IL-6 to activate STAT3, which is associated with aggressive oral cancer." (PMID 29664967, 2018). "In this study, we showed that GPRC5A expression was high in normal head and neck tissues, but it was gradually decreased in leukoplakia and greatly suppressed in head and neck cancer." (PMID 28270740, 2017). "We found that the average IHC score of GPRC5A is high in normal tissues (141.22 ± 66.975), whereas it was significantly lower in leukoplakia (76.00 ± 67.389), and greatly repressed in HNSCC (34.63 ± 41.389)." (PMID 28270740, 2017). "IHC analysis showed that, GPRC5A expression was high in normal tissue, but gradually decreased in oral leukoplakia, a precancerous stage, and greatly suppressed in primary cancer." (PMID 28270740, 2017). "In this study, we examined GPRC5A expression in normal tissue, leukoplakia and primary tumors." (PMID 28270740, 2017). "The results of this study showed that GPRC5A expression is gradually repressed in oral leukoplakia and HNSCC, suggesting that repression of GPRC5A pathway is involved in the multi-step process of head and neck carcinogenesis." (PMID 28270740, 2017). "Although the follow-up data in our leukoplakia patients has not been completed, our results suggest that the status of GPRC5A expression could enhance the predictability and reliability in cancer risk assessment of oral precancerous lesions, and possibly to improve the success of treatment." (PMID 28270740, 2017).
lung adenoma (2 papers, 2010 to 2023). A benign, well circumscribed epithelial neoplasm that arises from the bronchus or the lung parenchyma. "We have previously shown that mice with deletion of both alleles of the Gprc5a gene develop spontaneous lung adenomas and adenocarcinomas between the ages 12 and 24 months indicating that this gene is a mouse lung-specific tumor suppressor." (PMID 20686609, 2010). "The functional relevance of RAI3 expression in benign lung was previously highlighted by earlier studies demonstrating that GPRC5A-knockout mice spontaneous develop lung adenomas and adenocarcinomas and that loss of heterozygosity of chromosome 12p13 is a common alteration in NSCLCs." (PMID 36781501, 2023). "Previously, we have identified the Gprc5a gene as a mouse lung-specific tumor suppressor after finding that mice lacking both alleles of this gene develop spontaneous lung adenomas and adenocarcinomas unlike their wild-type littermates." (PMID 20686609, 2010).
metastatic tumors (2 papers, 2016 to 2020). "Additionally, GPRC5A was associated with shorter PFS in the metastatic tumors." (PMID 32115889, 2020). "In both groups, high GPRC5A was significantly associated with worse overall survival (OS) and with shorter progression‐free survival (PFS) in the metastatic tumors (OS: P = 0.044 and 0.012, PFS: P = 0.009)." (PMID 32115889, 2020). "To examine the correlation between GPRC5A and patient outcome, we performed survival analyses for primary and metastatic tumors separately." (PMID 32115889, 2020). "As can be seen from the same figure, metastatic tumors had an even higher average expression of GPRC5A compared with primary tumors." (PMID 27415424, 2016). "Since GPRC5A remains uncharacterized in clinical HGSC, we performed histological analysis of tissue microarrays (TMA) containing samples from primary and metastatic tumors of 126 treatment‐naïve HGSC patients." (PMID 32115889, 2020).
pancreatitis (2 papers, 2021). Inflammation of the pancreas. "Both in PaCa patients with pancreatitis or without pancreatitis, GPRC5A expression was higher than normal pancreas." (PMID 33753999, 2021). "Of note, between the two groups, patients with pancreatitis showed higher GPRC5A expression than those without pancreatitis (P<0.05)." (PMID 33753999, 2021). "Meanwhile, no significance relationship was found between GPRC5A and IMUP expression with patients pancreatitis status." (PMID 34819098, 2021).
triple-negative breast carcinoma (2 papers, 2020 to 2024). An invasive breast carcinoma which is negative for expression of estrogen receptor (ER), progesterone receptor (PR), and human epidermal growth factor receptor 2 (HER2). "In the present study, we investigated the roles of G-protein-coupled receptor family C, member 5, group A (GPRC5A) in cell apoptosis in triple-negative breast cancer (TNBC)." (PMID 33680947, 2020). "Taken together, the present study identified GPRC5A as a protective factor against the progression of human triple-negative breast cancer by increasing cell apoptosis via the regulation of the PI3K/Akt signaling pathway." (PMID 33680947, 2020). "GPRC5A was found to be downregulated in triple-negative breast cancer (TNBC), and its overexpression induced cell apoptosis by regulating the PI3K/Akt signaling pathway, suggesting that GPRC5A serves as a protective factor against TNBC progression by enhancing apoptosis.." (PMID 38634049, 2024).
acute lung injury (1 paper, 2015). A condition of lung damage that is characterized by bilateral pulmonary infiltrates (pulmonary edema) rich in neutrophils, and in the absence of clinical heart failure. "Previously, in the model of endotoxin-induced acute lung injury (ALI), NF-κB target gene expression was greatly activated in lungs from Gprc5a−/− mice compared to wild-type ones following administration of endotoxin, with a peak of activation within 2–24 hour." (PMID 26447616, 2015).
colitis (1 paper, 2021). Inflammation of the colon. "A vivo mouse model found that a lack of GPRC5A inhibited colitis-associated tumorigenesis." (PMID 33788883, 2021).
colorectal tumour (1 paper, 2018). "Although detectable levels of GPRC5A protein were present in normoxia, GPRC5A was robustly upregulated by hypoxia in all colorectal tumour cell lines tested." (PMID 30143543, 2018). "Importantly, we show that upregulation of GPRC5A during hypoxia protects colorectal tumour cells from apoptosis by activating the Hippo pathway effector YAP." (PMID 30143543, 2018).
corneal disease (1 paper, 2024). "Here, we report that WFDC2 and GPRC5A expression may be a novel marker for the corneal epithelial cells and subsequent EVs, but their functional role has yet to be determined, with WFDC2 and GPRC5A reported only in non-corneal disease models." (PMID 39408670, 2024).
diabetes (1 paper, 2021). "For oncogenes related to OBT2D vs. OBF, a correlation was found for GPRC5A and LINC00312 with glycemia and NKX3-1, GPRC5A and LINC00312 with insulinemia, as these are parameters which are significantly different in diabetes." (PMID 33671464, 2021).
Hypertension (1 paper, 2014). The presence of chronic increased pressure in the systemic arterial system. "‘Unknown I’ contained a diverse set of key driver genes such as SGK1, SIK1 and SLC10A6 (sodium metabolism and hypertension), MT2A and TSC22D3 (glucocorticoid signaling), GADD45G, ERRFI1, GPRC5A, and EGFR (cell growth and apoptosis), and CEBPB, CEBPD, and KCNA5 (heart development and function)." (PMID 25033284, 2014).
intrahepatic cholangiocarcinoma (1 paper, 2014). A carcinoma that arises from the intrahepatic bile duct epithelium in any site of the intrahepatic biliary tree. "On the other hand, in intrahepatic cholangiocarcinoma (ICC), GPRC5A mRNA levels are higher than in normal tissue suggesting that they could serve as a novel biomarker for classifying and diagnosing this highly fatal type of carcinoma." (PMID 25621293, 2014).
mesothelioma (1 paper, 2014). A usually malignant and aggressive neoplasm of the mesothelium which is often associated with exposure to asbestos. "GPRC5A acts as oncogene or tumor suppressor in different types of cancer but nothing is known about GPRC5A in mesothelioma." (PMID 25469901, 2014). "Thus, it might be reasonable to evaluate the potential roles of miR-103a-3p and GPRC5A in mesothelioma." (PMID 25469901, 2014).
myelodysplastic syndrome (1 paper, 2014). A clonal hematopoietic disorder characterized by dysplasia and ineffective hematopoiesis in one or more of the hematopoietic cell lines. "In myelodysplastic syndrome (MDS), GPRC5A mRNA levels were found to be lower in CD34+ cells, which could explain these cells' susceptibility to cell damage." (PMID 25621293, 2014).
osteoporosis (1 paper, 2025). A condition of reduced bone mass, with decreased cortical thickness and a decrease in the number and size of the trabeculae of cancellous bone (but normal chemical composition), resulting in increased fracture incidence. "They suggested that Gprc5a is a PTH (Parathyroid Hormone)-dependent gene that inhibits cell proliferation and osteoblast differentiation, and might be a suitable candidate as a drug target for osteoporosis." (PMID 40427604, 2025).
pneumonia (1 paper, 2020). An acute, acute and chronic, or chronic inflammation focally or diffusely affecting the lung parenchyma, caused by an infection in one or both of the lungs (by bacteria, viruses, fungi, or mycoplasma.). "Importantly, Sca-1+Abcg1+ and SPA+ABCG1+ cells specifically existed in the small bronchioles of Gprc5a-KO mice and patients with pneumonia, respectively." (PMID 32157214, 2020).
silicosis (1 paper, 2015). Silicosis is a respiratory disease caused by breathing in (inhaling) silica dust. "Here, we showed that GPRC5A genotype is a factor affecting host susceptibility to silicosis." (PMID 26447616, 2015).
situ carcinoma (1 paper, 2020). "We found that the percentage of the Sca-1+Abcg1+subset within the in situ carcinoma tissue reached 2.5%, which was higher than the percentage observed in lung tissue samples from Gprc5a-deficient mice that had not yet developed tumors." (PMID 32157214, 2020).
Tinnitus (1 paper, 2023). Tinnitus is an auditory perception that can be described as the experience of sound, in the ear or in the head, in the absence of external acoustic stimulation. "Meanwhile, down-regulated genes between the tinnitus and the control group were Car3, Egr2, Bcl6b, C1qtnf12, Cartpt, LOC108348062, Nr4a3, Gprc5a, LOC103690128, and Angptl6." (PMID 37190538, 2023).
virus infection (1 paper, 2023). "GPRC5A belongs to a family of proteins that are often reported to function at the top of the signalling cascade, although their role in virus infection is yet to be fully determined." (PMID 37376680, 2023).